CTLA4 (cytotoxic T-lymphocyte associated protein 4)
Diseases named in the same sentence as CTLA4 in open-access papers (continued):
Sharing a sentence is not in itself a finding about the gene and the disease.
rheumatoid arthritis (continued). "In rheumatoid arthritis, co-treatment with anti-TNFα and anti-IL1 mAbs and the combination of anti-TNFα mAb and abatacept (CTLA4-Fc/T-cell activation inhibitor) have been evaluated." (PMID 41409758, 2025). "For two putative core genes—CTLA4 and PDCD1—there is at least preliminary evidence of efficacy against rheumatoid arthritis in clinical trials of drugs that target the protein." (PMID 39887658, 2025). "In general, in patients with rheumatoid arthritis who have experienced primary failure to an anti-TNF-alpha drug, switching to a different therapeutic target (IL-6, CTLA-4, JAK) is postulated to be more effective than cycling to another anti-TNF-alfa." (PMID 39685848, 2024). "CTLA-4-Ig (Abatacept) is a US Food and Drug Administration (FDA)-approved drug primarily used for rheumatoid arthritis treatment." (PMID 37818377, 2023). "In addition, CTLA-4 Ig (abatacept) is being used to treat a number of autoimmune conditions, such as rheumatoid arthritis (RA) and type 1 diabetes." (PMID 38022598, 2023). "Specifically Abatecept, a fusion protein of CTLA-4 and IgG1 Fc portion (CTLA-4-Ig), is approved for abrogating immune overactivity in rheumatoid arthritis." (PMID 33569063, 2020). "CTLA4-Ig abatacept is an inhibitor that targets CD80 (also known as B7.1) and is currently used for rheumatoid arthritis (RA)." (PMID 32420329, 2020). "CTLA-4-Ig, an IgG Fc fusion homodimer of the extracellular domain of CTLA-4, which is currently approved therapeutic agent for rheumatoid arthritis, substantially inhibited IL-2 secretion from Jurkat cells, regardless of RGMB expression levels." (PMID 31061392, 2019). "Cytotoxic T lymphocyte-associated antigen-4-immunoglobulin (CTLA4-Ig) binding to the B7 molecules on antigen-presenting cells downregulates this activation and represents a recent biological treatment in rheumatoid arthritis (RA)." (PMID 19930661, 2009). "In contrast to PD-1/PD-L1 and CTLA-4, where agonistic approaches have therapeutic benefit, blockade of ICOS or its ligand (ICOSL) reduces disease severity in murine models of rheumatoid arthritis, such as the glucose-6-phosphate isomerase (GPI)-induced arthritis model." (PMID 41007749, 2025). "CTLA-4-Ig (Abatacept), a drug that combines the extracellular domain of CTLA-4 with the Fc region of an immunoglobulin, has been FDA-approved as a treatment for rheumatoid arthritis, active psoriatic arthritis." (PMID 37818377, 2023). "The concept of interfering with T cell costimulation to treat autoimmune diseases has been clinically validated with abatacept (CTLA-4-Ig), an approved CD28 pathway inhibitor for rheumatoid arthritis (RA), juvenile idiopathic arthritis, and psoriatic arthritis." (PMID 34986869, 2022). "The diagnosis was revised as possible rheumatoid arthritis-like psoriatic arthritis and adalimumab was replaced by abatacept (IgG1 Fc-CTLA-4) to no avail." (PMID 31165299, 2019). "Abatacept, a CTLA4-Ig fusion protein attenuates T cell activation by inhibiting the CD80/86-CD28 costimulatory pathway that is required for the proper T cell activation and thus displays beneficial effects in the treatment of rheumatoid arthritis (RA)." (PMID 29259723, 2017). "As with the original DMG-alone analysis, the MEGs were also significantly 3.75-fold enriched in the KEGG ‘Rheumatoid arthritis‘ pathway (q = 1.70E-02, where q is a multiple-test corrected P-value) with 7 out of 89 genes: ANGPT1, CSF2, CTLA4, HLA-DQA1, HLA-DQA2, HLA-DRA and HLA-DRB1." (PMID 25901943, 2015). "Cytotoxic T-lymphocyte antigen 4 (CTLA-4) is a key negative costimulatory molecule that displays a wide range of anti-inflammatory properties and is currently approved to treat rheumatoid arthritis as a recombinant fusion protein (CTLA4IgG)." (PMID 22369699, 2012). "It has been demonstrated that SNPs in PD-1, but not in CTLA-4, are associated with susceptibility to systemic lupus erythematosus (SLE) and rheumatoid arthritis (RA)." (PMID 21403914, 2011).
rheumatoid arthritis (continued). "Other genes (HAVCRI, CTLA4, SUMO4, MAP3K7IP2, PAID4, chromosome 5 locus, MIF) may also contribute to the development of rheumatoid arthritis directly or within the context of smoking." (PMID 18466513, 2007). "It has been reported that using CTLA-4 fusion protein to block the interaction between CD28 and B7 can inhibit the autoimmune response in experimental rheumatoid arthritis (RA)." (PMID 38524638, 2024). "In a similar cross-sectional case–control study with rheumatoid arthritis patients, we examined the levels of serum sCD26 and DPP4 activity in patients’ groups defined according to the therapies (conventional or biological) with anti-TNF, anti-CD20, anti-IL6R, or Ig-CTLA4." (PMID 39001488, 2024). "Over the last 30 years, the treatment of rheumatoid arthritis (RA) has been revolutionized with the development of biologic therapies such as anti-TNF, anti-IL-6, CTLA4-Ig and anti-CD20 agents, among others." (PMID 30886973, 2018). "Furthermore, in a rheumatoid arthritis synovium SCID mouse model it was shown that only neutralization of IL-17 but not application of CTLA-4-Ig has a therapeutic effect on CD3-rich samples." (PMID 26172046, 2015). "This CD4− cluster largely expressed Foxp3, Helios, and TIGIT as well as CD25, CD39, CTLA-4, CD71, HLA-DR, and low CD127, thus mirroring CD8+ Treg-like cells which have been described in inflamed joints of rheumatoid arthritis (RA), psoriatic arthritis (PsA), and spondylarthritis." (PMID 39101538, 2024). "Abatacept, a CTLA4-Ig fusion protein, attenuates T cell activation by inhibiting the CD80/CD86–CD28 costimulatory pathway that is required for the proper T cell activation and thus displays beneficial effects in the treatment of rheumatoid arthritis (RA)." (PMID 29259723, 2017).
colon carcinoma (165 papers, 2012 to 2026). "The knockout of autophagy-related genes RB1CC1, ATG9A, and ATG12 significantly increased tumor cell susceptibility to T-cell killing in breast and colon cancers and enhanced the anti-cancer effect of PD-1 and CTLA-4 checkpoint inhibitors." (PMID 40641524, 2025). "High-risk colon cancer patients also demonstrate increased activity of immune checkpoint molecules such as PD-1 and CTLA-4, which hinder T-cell function and their capacity to target cancer cells." (PMID 38594466, 2024). "Treg cells in human colon tumor tissues express immunosuppressive molecules such as PD-1, cytotoxic T-lymphocyte-associated protein-4 (CTLA-4), T cell immunoglobulin and mucin domain-3 (TIM-3) and lymphocyte-activation gene 3 (LAG-3)." (PMID 36982677, 2023). "The immunotherapeutic potential of LP in combination with α-programmed cell death protein-1 (PD-1) or α-cytotoxic T-lymphocytes-associated protein 4 (CTLA-4) was evaluated in syngeneic MC38 colon cancer and B16F10 melanoma." (PMID 35764365, 2022). "Concerning CD8 T cells, the peripheral blood-circulating CX3CR1+ CD8 T-cell frequency is associated with the ICB (anti-PD-1, anti-CTLA-4 or both) efficacy in murine colon cancer models." (PMID 36429101, 2022). "We found that common checkpoints such as CD274, CEACAM1, HAVCR2, and CTLA4 in the treatment of colon cancer were significantly correlated with risk score." (PMID 34840571, 2021). "We also noticed that the upregulation of IDO1 frequently co-occurred with the upregulation of PD-1, CD274 (also known as programmed death ligand 1, PD-L1), and cytotoxic T-lymphocyte-associated protein 4 (CTLA4) in colon cancer." (PMID 33425745, 2020). "In one study, treatment with anti-PD-1 or anti-PD-L1 or anti-CTLA4 alone caused CT-26 colon tumors to be rejected in 25%, 33%, and 50% of the mice injected, respectively, which increased to 75% with dual blockade." (PMID 26510455, 2015). "Notably, we identified for the first time that anti-PD-L1 or anti-CTLA-4 antibodies may decrease the OS of specific colon cancer patients in the low-risk group." (PMID 35692800, 2022). "Therefore, better benefits may be achieved when immunotherapeutic drugs (PD1/PDL-1/PD-L2/CTLA-4 blockers) are used for colon cancer patients in the low-risk score group." (PMID 35991564, 2022). "Taking into consideration our results indicating that colon tumors from AA patients appear to have an impaired cytotoxic tumor environment, we examined the expression of immunotherapy targets Programmed cell Death-1 (PD-L1) and cytotoxic T-lymphocyte-associated protein 4 (CTLA-4) in our samples." (PMID 32983990, 2020). "At peak liver fibrosis, where CD8 T cell hyperfunction was observed, mice were challenged with subcutaneous (s.c.)implantation of MC38 colon carcinoma cells, followed by anti‐PD‐1 and anti‐CTLA‐4 combined immunotherapy after tumour volumes reached ≈75 mm3." (PMID 40760842, 2025). "We decided to investigate the antitumor activity of IL-2cx (2 μg IL-2/dose) either alone or in combination with ICIs (anti-CTLA-4 plus anti-PD-1 antibodies) using the CT26 mouse colon carcinoma model." (PMID 40789741, 2025). "Lysates of Lactobacillus acidophilus combined with CTLA-4-blocking antibodies enhance antitumor immunity in a mouse colon cancer model." (PMID 41472726, 2025). "published that TNF-α blockers not only ameliorate the anti-tumor effect of anti-PD-1 and anti-CTLA-4 combination, but at the same time, reduce irAEs in a preclinical mouse model of colon cancer." (PMID 40433358, 2025). "PD1/CTLA‐4 BsAb significantly inhibits tumors in MC38 colon cancer‐bearing mice more effectively than the combination of aPD1 and aCTLA‐4, with tumor suppression rates of 96.8% and 77.3%, respectively." (PMID 39606809, 2025). "In contrast to CTLA-4 and PD-1 checkpoint molecules, TIGIT is associated with NK cell exhaustion in mice with tumors and patients with colon cancer." (PMID 40567374, 2025).
colon carcinoma (continued). "Lactobacillus acidophilus lysate in combination with CTLA-4 helps to enhance anti-tumor immune response in colon cancer mice by decreasing Treg and M2 macrophage infiltration, and increasing the number of CD8+ T cells in the TME." (PMID 40873588, 2025). "In colon cancer models, combining neoantigen vaccination with CTLA-4 blockade led to improved neoantigen-specific T cell responses and complete tumor regression." (PMID 41024300, 2025). "In the Van Allen cohort 2015 pairs, we found that high expression of SERPINC1 renders colon cancer patients resistant to treatment with anti‐CTLA‐4." (PMID 38923313, 2024). "Clonotypes with CASSPGQANTEVFF and CASSDRVEQYF CDR3s were found in anti-CTLA-4-responsive mice with MC38 colon cancer and during response to allogeneic skin graft, respectively." (PMID 38675728, 2024). "Linear regression analyses demonstrated a positive significant correlation between Al levels and CTLA4 expression in colon cancer lesions (p < 0.0001; R-squared = 0.85)." (PMID 39769153, 2024). "The study investigated how lysates of Lactobacillus acidophilus combined with CTLA-4-blocking antibodies (CTLA-4 IgG (clone# 9H10)) enhanced anti-tumor immunity in a BALB/c mouse model of colon cancer." (PMID 39273009, 2024). "Here, we utilized a PD-1/PD-L1/CTLA-4 humanized BALB/c mice with established CT26-hPD-L1 colon carcinoma." (PMID 37711295, 2023). "Moreover, we demonstrated that the risk score signature based on the screened FAM genes could distinguish the immune subtypes in patients with colon cancer, and the risk score was positively correlated with the expression of immune checkpoint molecules such as PD-1, PD-L2 and CTLA4." (PMID 38045683, 2023). "In this study, we investigated the potential of a liposome-based nanoparticle (CRT-NP) expressing calreticulin as an in-situ vaccine to restore sensitivity to anti-CTLA4 immune checkpoint inhibitor (ICI) in CT26 colon tumors." (PMID 37376141, 2023). "Relative quantification of CTLA-4 gene expression was performed by quantitative real-time (q-RT) PCR from 31 colon cancer fresh tissues and 30 normal adjacent matching tissues." (PMID 37107632, 2023). "In line with our study, the efficacy of anti-CTLA-4 antibody was reported in other murine tumor models of colon cancer (ie., CT26, Colon 26, and MC38) which showed high sensitivity and durable responses to CTLA-4 blockade." (PMID 37711295, 2023). "Among the remarkable advancements in this field are ICIs, such as PD-1 and CTLA-4 inhibitors, which have shown remarkable efficacy in various cancers, including colon cancer." (PMID 37692610, 2023). "At present, the only ICI approved for the treatment of colon cancer are PD-1/PD-L1 inhibitors and CTLA-4 inhibitors." (PMID 37629096, 2023). "By comparing paired tumour samples from patients with MMR-d colon cancer that were obtained before and after dual PD-1 and CTLA-4 blockade, we found that immune checkpoint blockade substantially increased the frequency of γδ T cells in B2M-deficient cancers." (PMID 36631610, 2023). "As with PD-1 and CTLA-4, mAbs targeting these emerging immune checkpoints are under clinical investigation for colon cancer treatment." (PMID 37692610, 2023). "The administration of anti‐CTLA‐4 antibody after injecting cyclophosphamide significantly inhibits the tumor progression in the CT26 colon carcinoma model, while the reverse administration sequence leads to the apoptosis of anti-tumor CD8+ T cells." (PMID 36703971, 2022). "Anti-CTLA-4 also repressed lung metastasis burden in our experimental metastasis CT-26 model suggesting particular interest of CTLA-4 blockade for advanced colon cancer." (PMID 35339889, 2022). "Larimer and colleagues have shown a high level of infiltration of T-cells during anti-CTLA4 treatment by targeting the T-cell surface glycoprotein CD3 in colon cancer xenograft models using a murine 89Zr-labelled anti-CD3." (PMID 35099641, 2022).
colon carcinoma (continued). "Epigenetic alterations such as DNA methylation have been widely reported to regulate expression of key immune checkpoint proteins including PD-L1 and CTLA-4 in breast and colon cancer." (PMID 35711675, 2022). "It is reported that dual CTLA-4 and PD-L1 blockade has an excellent performance in inhibiting tumor growth and liver metastasis in a highly aggressive orthotopic mouse model of colon cancer." (PMID 35912258, 2022). "In this study, we demonstrated that CT-26 colon cancer and 4T1 triple negative breast cancer have different sensitivity to anti-PD-1 and anti-CTLA-4 therapy." (PMID 35339889, 2022). "Colon cancer in cluster 1 displayed significantly higher PD-1 and CTLA4 IPS, and showed significantly higher levels of TMB and ratio of MSI-H." (PMID 35962309, 2022). "In summary, we showed that AHCC® promoted the tumor suppressive effect of dual PD-1 and CTLA-4 blockade in mice bearing MC38 colon cancer through possibly affecting the gut microbiome." (PMID 35514996, 2022). "We identified that in APC-wt/MSS colon cancer, the expressions of PD-1, PD-L1, CTLA4, and CYT (GZMA and PRF1) were increased." (PMID 35937946, 2022). "Immunotherapy drugs (PD1/PD-L1 blocker and CTLA-4 blocker) have been shown to improve the prognosis of colon cancer patients." (PMID 35991564, 2022). "CTLA-4, PD-1, and PD-L1 are responsible for the immunotherapeutic responses in patients with colon cancer." (PMID 36280825, 2022). "According to the latest NCCN colon cancer guidelines (2021 V2), PD-1 inhibitors or PD-1 inhibitors combined with low-dose CTLA4 inhibitors can be used as first-line treatments for dMMR/MSI-H metastatic colon cancer." (PMID 35677634, 2022). "We also demonstrated that CTLA-4 targeting reduced metastasis formation in the colon cancer metastasis model." (PMID 35339889, 2022). "Dysbiosis of the gut microbiota hampers the anticancer effect of CTLA-4 Ab in the MC38 colon cancer model." (PMID 34938284, 2021). "In colon cancer syngeneic mouse models, researchers revealed that the co-administration of L. acidophilus cell lysates with anti-CTLA-4 therapy significantly protected against tumor development." (PMID 34360802, 2021). "Then, the authors went on to study the combination therapy of PTT-PLGA-ICG-R837 NPs and anti-CTLA-4 mAb in an artificial metastasis model of breast or colon cancer." (PMID 33800368, 2021). "In preclinical experiments on a murine colon cancer model (CT-26), a double blockade of CTLA-4 and PD-L1 enhanced tumor rejection and completely inhibited liver metastasis, while blocking CTLA-4 or PD-L1 alone caused a decrease in liver metastasis." (PMID 34572263, 2021). "MC38 adenocarcinoma colon tumors in mice responded to targeted anti-PD-1 or anti-CTLA-4 antibodies; however, this response was impaired in the gnotobiotic mice group or with the administration of antibiotics prior to immunotherapy." (PMID 34360802, 2021). "The rationale is based on the observation of systemic tumor responses (abscopal effect) in metastatic, MSS pancreatic or colon cancer—i.e., tumors notoriously resistant to immune checkpoint inhibitors—when combining PD-1/CTLA-4 inhibitors with radiotherapy." (PMID 33805461, 2021). "Recently, PD-1 plus CTLA-4 blockade was demonstrated as highly effective in early-stage dMMR colon cancers." (PMID 32968876, 2021). "The potential of inhibiting CTLA-4 for cancer therapy was observed in vivo when administration of anti-CTLA-4 antibodies resulted in rejection of murine colon carcinoma and fibrosarcoma and generation of immunological memory." (PMID 33207697, 2020). "Nonetheless, further evaluation of patients’ prognoses and immunotherapy efficacy beyond the contributions from T cell infiltration, PD-1/PD-L1 and CTLA4 in colon cancer is necessary." (PMID 33425745, 2020). "Anti-4-1BB mAb treatment also improved the therapeutic response to CTLA-4 mAb in colon cancer models." (PMID 32391001, 2020).